TLNRD1 (talin rod domain containing 1)
Description:
Actin-binding protein which may have an oncogenic function and regulates cell proliferation, migration and invasion in cancer cells.
Synonyms: MESDC1; MGC99595
Tractability: PROTAC: ubiquitination databases record sites on it.
Gene: Protein-coding gene on chromosome 15 (81,000,923 to 81,005,788, forward strand). Ensembl gene ENSG00000140406.
Subcellular location (Human Protein Atlas): Cytoplasmic bodies; Nucleoplasm
Gene Ontology:
Molecular function: identical protein binding; protein binding; actin binding
Cellular component: stress fiber
Genetic constraint (gnomAD): Loss-of-function variants: 14 observed, 12.94 expected, observed/expected ratio (o/e) 1.08, 90% interval 0.71 to 1.66. The synonymous counts are far from expectation, so gnomAD's model fits this gene poorly and the ratio says little. Missense variants: 569 observed, 416.78 expected, observed/expected ratio (o/e) 1.37, 90% interval 1.27 to 1.46. Synonymous variants: 345 observed, 208.13 expected, observed/expected ratio (o/e) 1.66, 90% interval 1.52 to 1.81.
Homologues: Orthologues: macaque TLNRD1 (99% identical), pig TLNRD1 (99% identical), mouse Tlnrd1 (98% identical), rat Tlnrd1 (98% identical), dog TLNRD1 (98% identical), guinea pig TLNRD1 (95% identical), rabbit TLNRD1 (86% identical), tropical clawed frog tlnrd1 (74% identical), zebrafish tlnrd1 (70% identical), Drosophila melanogaster rhea (25% identical), Caenorhabditis elegans tln-1 (19% identical). Paralogues in human: TLN1 (33% identical), TLN2 (31% identical).
Diseases named in the same sentence as TLNRD1 in open-access papers:
TLNRD1 is named in the same sentence as 10 diseases in open-access papers, as found by Europe PMC text mining. Sharing a sentence is not in itself a finding about the gene and the disease. The quoted sentences say what the papers report.
bladder cancer (9 papers, 2012 to 2024). "Other studies have shown that TLNRD1 overexpression is associated with increased proliferation and xenograft growth in hepatocellular carcinoma and that TLNRD1 depletion reduced bladder cancer cell migration and invasion." (PMID 39013281, 2024). "In contrast, TLNRD1 depletion reduced bladder cancer cell viability, migration, and invasion, and data from multiple databases show that high TLNRD1 mRNA levels often correlate with poor lung cancer patient survival." (PMID 34264272, 2021). "Mesoderm development candidate 1 (MESDC1), also known as TLNRD1, is confirmed as an oncogenic function in bladder cancer and hepatocellular carcinoma." (PMID 33968141, 2021).
hepatocellular carcinoma (6 papers, 2020 to 2024). A malignant tumor that arises from hepatocytes. "Previous studies have shown that TLNRD1 is directly targeted by anti-oncogenic miRNAs, with TLNRD1 overexpression being associated with increased proliferation and xenograft growth in hepatocellular carcinoma." (PMID 34264272, 2021).
cerebral cavernous malformation (1 paper, 2024). A disorder characterized by malformations in the structure of the capillaries in the brain. "We demonstrate that TLNRD1 is a component of the cerebral cavernous malformations (CCM) complex through its direct interaction with CCM2, which is mediated by a hydrophobic C-terminal helix in CCM2 that attaches to a hydrophobic groove on the four-helix domain of TLNRD1." (PMID 39013281, 2024).
dilated cardiomyopathy (1 paper, 2024). Cardiomyopathy which is characterized by dilation and contractile dysfunction of the left and right ventricles. "TLNRD1 is also overexpressed in patients with dilated cardiomyopathy and ischemic heart disease and is associated with significant stroke risk." (PMID 39013281, 2024).
lung carcinoma (1 paper, 2021). "As filopodia often contribute to invasive migration of cancer cells, and as increased TLNRD1 mRNA levels correlate with poor outcomes in lung cancer, future work will focus on the contribution of TLNRD1 to invasive cell migration." (PMID 34264272, 2021).
cancer (3 papers, 2021 to 2024). A tumor composed of atypical neoplastic, often pleomorphic cells that invade other tissues. "In cancer cells, TLNRD1 localizes to the cytoplasm and accumulates on actin bundles and in filopodia." (PMID 39013281, 2024). "Functionally, we reported that TLNRD1 expression enhanced filopodia formation and cancer cell migration, while TLNRD1 downregulation had the opposite effect." (PMID 39013281, 2024). "While TLNRD1 appears to modulate cancer cell functions, little is known about the physiological functions of TLNRD1 in normal tissue." (PMID 39013281, 2024). "We previously showed that TLNRD1 and ITGB1BP1 accumulate at the tips of myosin-X (MYO10)-induced filopodia in cancer cells." (PMID 39013281, 2024). "Importantly, we identified a series of ZnO NPs-responsive genes, including TLNRD1 and CCNB1IP1, that promote cancer cell death under ZnO NPs treatment." (PMID 34620733, 2021).
TLNRD1 also shares sentences with these, for which no sentence is quoted: tumor (3 papers); ischemic heart disease (1); liver cancer (1); Stroke (1).